GREM2 (gremlin 2, DAN family BMP antagonist)
Description:
Cytokine that inhibits the activity of BMP2 and BMP4 in a dose-dependent manner, and thereby modulates signaling by BMP family members. Contributes to the regulation of embryonic morphogenesis via BMP family members. Antagonizes BMP4-induced suppression of progesterone production in granulosa cells.
Synonyms: CKTSF1B2; DAND3; PRDC; FLJ21195; STHAG9
Tractability: Antibody: UniProt places it where antibodies can reach, with high confidence; its Gene Ontology location is reachable by antibodies, with high confidence; UniProt predicts a signal peptide or a membrane-spanning region.
Gene: Protein-coding gene on chromosome 1 (240,489,573 to 240,612,155, reverse strand). Ensembl gene ENSG00000180875.
Subcellular location: Secreted
Pathways (Reactome):
Signal Transduction: Signaling by BMP
Gene Ontology:
Molecular function: BMP binding; heparin binding; receptor ligand activity; identical protein binding; protein sequestering activity
Biological process: cytokine-mediated signaling pathway; embryonic body morphogenesis; regulation of cytokine activity; determination of dorsal identity; negative regulation of BMP signaling pathway
Cellular component: extracellular region
Genetic constraint (gnomAD): Loss-of-function variants: 11 observed, 14.88 expected, observed/expected ratio (o/e) 0.74, 90% interval 0.46 to 1.22. The upper end of that interval is the gene's LOEUF score, 1.22, which puts it in group 5 of 6, group 1 being the genes least tolerant of losing a copy. Missense variants: 210 observed, 232.29 expected, observed/expected ratio (o/e) 0.9, 90% interval 0.81 to 1.01. Synonymous variants: 98 observed, 104.06 expected, observed/expected ratio (o/e) 0.94, 90% interval 0.8 to 1.11.
Homologues: Orthologues: chimpanzee GREM2 (100% identical), macaque GREM2 (100% identical), guinea pig GREM2 (98% identical), mouse Grem2 (95% identical), rat Grem2 (95% identical), zebrafish grem2b (71% identical), pig GREM2 (71% identical), rabbit GREM2 (65% identical), zebrafish grem2a (61% identical), Caenorhabditis elegans F35B12.10 (30% identical). Paralogues in human: GREM1 (57% identical), NBL1 (23% identical).
Diseases named in the same sentence as GREM2 in open-access papers:
GREM2 is named in the same sentence as 46 diseases in open-access papers, as found by Europe PMC text mining. Sharing a sentence is not in itself a finding about the gene and the disease. The quoted sentences say what the papers report.
osteoporosis (7 papers, 2016 to 2025). A condition of reduced bone mass, with decreased cortical thickness and a decrease in the number and size of the trabeculae of cancellous bone (but normal chemical composition), resulting in increased fracture incidence. "In the Yu Feng’s study showed that the GREM2 gene polymorphisms were positively associated with the risk of osteoporosis in postmenopausal women." (PMID 35983515, 2022). "Several recent studies have addressed the relationship between GREM2 gene polymorphism and the risk of osteoporosis." (PMID 32297643, 2020). "Genetic variants of GREM2 are associated with BMD, and GREM2 is considered a susceptibility gene for osteoporosis." (PMID 28536615, 2016). "Therefore, the present study recruited 310 patients with osteoporosis and 339 healthy postmenopausal women to assess the correlation of GREM2 gene polymorphisms with the risk of osteoporosis." (PMID 32297643, 2020). "The present study also investigated whether GREM2 rs4454537 polymorphism was linked to the risk of osteoporotic fracture since this polymorphism conferred susceptibility to osteoporosis." (PMID 32297643, 2020). "GREM2 gene variants have been studied in various diseases, but rarely in osteoporosis." (PMID 32297643, 2020). "Therefore, this case–control study was designed as a means of exploring how GREM2 gene polymorphisms impact osteoporosis susceptibility, BMD levels, and fracture incidence." (PMID 32297643, 2020). "Thus, it is believed that GREM2 might be a prominent candidate gene for susceptibility to osteoporosis." (PMID 32297643, 2020). "However, GREM2 gene variants in osteoporosis were less frequent in a Chinese population." (PMID 32297643, 2020). "Our findings revealed that GREM2 rs4454537, not rs11588607, polymorphism increased osteoporosis risk in Chinese postmenopausal women, especially in subjects with BMI < 25 kg/m2." (PMID 32297643, 2020). "However, for osteoporosis, the L2-L4 BMD of the CC genotype was significantly lower than the TT genotype, indicating that GREM2 rs4454537 polymorphism showed a significant correlation with L2-L4 BMD." (PMID 32297643, 2020). "The results showed that GREM2 gene rs4454537, not rs11588607, polymorphism was significantly associated with an increased risk of osteoporosis in postmenopausal women." (PMID 32297643, 2020). "We believe that GREM2, being a BMP antagonist, is a promising new target for osteoporosis treatment." (PMID 38839844, 2024). "By targeting GREM2 to activate the BMP2/SMAD pathway, miR-671-3p may stimulate osteogenic differentiation, foster bone formation, and prevent the onset of osteoporosis." (PMID 40500779, 2025). "GREM2 expression was strong in the bone specimens of osteoporosis patients compared to people without osteoporosis, and human bone marrow stem cells (hBMSCs) mixed with Matrigel containing siRNA GREM2 were transplanted into defect areas of femoral bones in nude mice." (PMID 35883659, 2022).
prostate carcinoma (7 papers, 2020 to 2024). A carcinoma that arises from epithelial cells of the prostate gland. "Furthermore, we found that the prostate cancer-associated fibroblast-derived exosomes carrying miR-423-5p increased the resistance of PC cells to taxane by inhibiting GREM2 through the TGF-β pathway." (PMID 33144675, 2020). "Although the effect of GREM2 on cancer-associated fibroblasts in the breast cancer microenvironment is still unknown, exosomal miR-423-5p secreted by cancer-associated fibroblasts in prostate cancer is known to be able to promote chemotherapy resistance by inhibiting GREM2." (PMID 37880751, 2023). "Interestingly, EVs derived from cancer-associated fibroblasts (CAFs) contain miR-423-5p, and these CAF-EVs promote taxane resistance in prostate cancer by targeting gremlin-2 (GREM2) to activate the transforming growth factor beta (TGFβ) pathway." (PMID 36835116, 2023). "Additionally, to verify that miR-423-5p carried by the CAF-derived exosomes promoted chemotherapy resistance in prostate cancer by targeting GREM2, we selected 22Rv-1/TAX cells for functional rescue experiments." (PMID 33144675, 2020). "Still, in prostate cancer, CAF-derived exosomes miR-423-5p inhibited the GREM2 (Gremlin 2) gene via the TGF-β pathway, increasing resistance to taxane." (PMID 37784082, 2023). "Specifically, miR-423-5p transported by the CAFs-derived exosomes can promote resistance to taxane by targeting gremlin 2 (GREM2) and promoting TGF-β signaling in prostate cancer." (PMID 34852849, 2021).
breast carcinoma (3 papers, 2019 to 2023). "Thus, further studies are needed to examine the relationship between GREM2 and cancer-associated fibroblasts in breast cancer." (PMID 37880751, 2023). "Proliferative and invasive abilities of breast cancer cells reduced by adipocytes-Grem2 were restored by IL-6 treatment." (PMID 37880751, 2023). "In conclusion, we, for the first time, report that GREM2 overexpression in adipocytes can inhibit breast cancer proliferation and metastasis." (PMID 37880751, 2023). "In this context, further studies are needed to utilize GREM2 for gene therapy or to discover small molecules that can increase GREM2 expression in adipocytes to effectively treat breast cancer." (PMID 37880751, 2023). "An orthotopic breast cancer mouse model was used to examine the role of adipocytes-Grem2 in breast cancer progression." (PMID 37880751, 2023). "Our findings suggest that overexpressing GREM2 in adipocytes is a novel therapeutic approach to effectively inhibit breast cancer proliferation and metastasis." (PMID 37880751, 2023). "The mechanism by which GREM2 directly affects breast cancer cells requires further detailed studies." (PMID 37880751, 2023). "Proliferative and invasion abilities of spheroids formed by co-culturing MTV/TM-011 breast cancer cells and adipocytes-Grem2 were significantly reduced compared to those of spheroids formed by co-culturing MTV/TM-011 cells and adipocytes-mock." (PMID 37880751, 2023). "CM obtained from Grem2-overexpressing adipocytes decreased the proliferation of breast cancer cells compared to the control." (PMID 37880751, 2023). "To examine effects of Grem2-overexpressing adipocytes and IL-6 protein on invasive capacity of breast cancer cells, we performed a 3D invasion assay." (PMID 37880751, 2023). "The present study demonstrates that GREM2 can inhibit adipogenesis and that adipocytes overexpressing Grem2 play an important role in inhibiting breast cancer cell growth, migration, and metastasis." (PMID 37880751, 2023). "Next, we performed a co-spheroid invasion assay to determine the effect of Grem2-overexpressing adipocytes on invasion ability of breast cancer cells." (PMID 37880751, 2023). "3T3-L1-mock and 3T3-L1-Grem2 cells were differentiated into adipocytes (adipocytes-mock and adipocytes-Grem2) for 9 days and then mixed with breast cancer MTV/TM-011 cells at the same ratio to form 3D spheroids in ultra-low attachment plates." (PMID 37880751, 2023). "We used a 3D co-culture system of adipocytes and breast cancer cells to investigate the effect of GREM2-suppressed adipogenesis on breast cancer cells." (PMID 37880751, 2023). "As a result, it was confirmed that the proliferation of breast cancer cells (MTV/TM-011 or MDA-MB-231) treated with the CM obtained from adipocytes-Grem2 was significantly reduced compared to that of cells treated with CM obtained from adipocytes-mock." (PMID 37880751, 2023). "In particular, inhibition of the adipokine IL-6 by GREM2 had an effect in suppressing proliferation, migration, and metastasis of breast cancer cells in the breast cancer microenvironment." (PMID 37880751, 2023). "Taken together, these results indicate that overexpressing Grem2 in adipocytes can reduce breast cancer cell proliferation and lung metastasis in vivo and IL-6 can reverse these effects." (PMID 37880751, 2023). "To investigate the effect of adipocyte-Grem2 on breast cancer cells, we analyzed the proliferative and invasion abilities of spheroids using a 3D co-culture system of breast cancer cells and adipocytes or conditioned medium (CM) of adipocytes." (PMID 37880751, 2023). "The invasion ability of breast cancer cells, which was reduced by adipocyte-Grem2, was greatly restored by IL-6 treatment alone, but additional administration of Serpine1, another cytokine reduced by adipocyte-Grem2, had a greater effect on recovering cancer cell invasion." (PMID 37880751, 2023).
breast carcinoma (continued). "MTV/TM-011 breast cancer cells were treated with CM from mock- or Grem2-overexpressing adipocytes." (PMID 37880751, 2023). "We hypothesized that adipocytes overexpressing Grem2 could inhibit breast cancer cell proliferation and invasion by suppressing certain adipokines." (PMID 37880751, 2023). "Our study suggests that GREM2 overexpression in adipocytes can inhibit adipogenesis, reduce the expression and secretion of several adipokines, including IL-6, and ultimately inhibit breast cancer progression." (PMID 37880751, 2023). "In this study, we found that GREM2 suppressed adipocyte differentiation and that adipocytes overexpressing Grem2 reduced the production of several adipokines, including IL-6, contributing to the inhibition of breast cancer cell growth and lung metastasis." (PMID 37880751, 2023). "This study suggests that reduced expression of several adipokines in adipocytes overexpressing GREM2 may contribute to breast cancer suppression." (PMID 37880751, 2023). "Interestingly, the expression of IL-6 in breast cancer cells was significantly reduced by co-culture of adipocytes-Grem2." (PMID 37880751, 2023). "In addition, it is possible that GREM2 itself, secreted from GREM2-overexpressing adipocytes, has an effect on breast cancer suppression independently of adipokines." (PMID 37880751, 2023). "GREM2 inhibited adipogenesis and the production of the adipokines, including IL-6, in adipocytes, which likely makes an important contribution to the inhibition of breast cancer progression." (PMID 37880751, 2023). "As an adipogenic inhibitor, GREM2 could be developed as a target for obesity or a therapeutic means to inhibit breast cancer progression." (PMID 37880751, 2023). "Next, whether reduced expression and secretion of IL-6 in Grem2-overexpressing adipocytes had a direct effect on the proliferation of breast cancer cells was determined." (PMID 37880751, 2023). "Taken together, these results suggest that Grem2-overexpressing adipocytes have the potential to suppress the expression of cytokines, including IL-6, in adipocytes or breast cancer cells, which may contribute to the inhibition of breast cancer progression." (PMID 37880751, 2023). "Therefore, we checked whether Grem2 overexpression in adipocytes also affected the reduction of IL-6 expression in breast cancer cells." (PMID 37880751, 2023). "Additionally, our study suggests that GREM2, a type of cytokine, can be secreted when overexpressed in adipocytes and may directly contribute to the suppression of breast cancer independently of adipokines." (PMID 37880751, 2023). "Two breast cancer cell lines MTV/TM-011 and MDA-MB-231 were treated with CM obtained from adipocytes-mock or adipocytes-Grem2." (PMID 37880751, 2023). "In orthotopic breast cancer mouse model, mice injected with both MTV/TM-011 cells and adipocytes-Grem2 showed smaller primary tumors and lower lung metastasis than controls." (PMID 37880751, 2023). "After culturing adipocytes-mock or adipocytes-Grem2 on the transwells and MTV/TM-011 breast cancer cells on the bottom for 48 h, changes in IL-6 mRNA expression in breast cancer cells were examined." (PMID 37880751, 2023). "Moreover, amplification and/or upregulation of BMPs as well as BMP-antagonists, including NOG, GREM1, GREM2, and CHRD have been reported in breast cancer." (PMID 31694641, 2019). "For instance, GREM2 is commonly amplified in breast cancer patients, indicating that elevated levels of GREM2 origins from the cancer cells and not the surrounding tissue." (PMID 31694641, 2019).
idiopathic pulmonary fibrosis (3 papers, 2021 to 2024). Idiopathic pulmonary fibrosis (IPF) is a nonneoplastic pulmonary disease that is characterized by the formation of scar tissue within the lungs in the absence of any known cause. "GREM2, initially identified as a TGF-β-inducible gene, encodes a small secreted glycoprotein belonging to a group of matricellular proteins, its role in lung fibrosis is not clear." (PMID 34422900, 2021).
diabetes (2 papers, 2017 to 2025). "Given obesity is tightly linked with diabetes and β‐cell function, we speculated whether circulating Grem2 is associated with the development and treatment of diabetes in humans." (PMID 40270326, 2025). "Through this comprehensive study design, we will provide evidence of the impact of diabetes status and therapeutic interventions on circulating Grem2 levels and their relationship with β‐cell function." (PMID 40270326, 2025). "We first evaluated circulating Grem2 levels in 178 participants (59 with T2D and 119 without diabetes) who underwent a 3‐h OGTT." (PMID 40270326, 2025).
Hyperinsulinemia (2 papers, 2024 to 2025). An increased concentration of insulin in the blood. "Alternatively, the alterations in glucose homeostasis due to obesity may impair Grem2 signaling, resulting in a compensatory increase in Grem2 levels, akin to mechanisms seen in hyperinsulinemia and hyperleptinemia." (PMID 40270326, 2025). "In contrast, we observed the additive effect of hyperinsulinemia and JAKi on the cell cycle-controlling genes CDKN2D/p19, EIF2S3B, GREM2, and YBX3." (PMID 39768214, 2024).
meningioma (2 papers, 2019 to 2024). A generally slow growing tumor attached to the dura mater. "Moreover, strong GREM2 expression around the psammoma body of grade 1 meningiomas and at the sites of whorl formation suggested that the GREM2/BMP signal was strongly associated with tumor calcification and proliferative capacity." (PMID 38446374, 2024). "Our results suggest that decrease of GREM2 expression may be linked to acquisition of malignant behavior in meningioma." (PMID 31039818, 2019). "The effects of bone morphogenetic protein (BMP) signal inhibitor (K02288) and upstream regulator Gremlin2 (GREM2) on meningioma’s growth and senescence were examined." (PMID 38446374, 2024). "When analyzing these genes’ expression across each meningioma grade, we observed how GREM2, SNORA46, and SNORA48 were expressed at significantly higher levels in I NP when compared to I P, secondary or de novo grade II, and grade III." (PMID 31039818, 2019). "GREM2 was identified as one of the factors involved in malignant transformation of meningiomas by bioinformatics analysis, but the mechanism of GREM2 expression leading to suppression of BMP, the transforming growth factor-β signaling pathway, and tumor progression, was unclear." (PMID 38446374, 2024). "How the decrease of GREM2 expression that we observed in grade II-III meningiomas may lead to defects in BMP and/or TGFβ signaling and to tumor progression remains to be determined." (PMID 31039818, 2019). "We identify GREMLIN 2 (GREM2), a regulator of the BMP pathway, and the small nucleolar RNAs (snoRNAs) SNORA46 and SNORA48 as novel, previously uncharacterized, downregulated candidate genes that may be linked to meningioma progression." (PMID 31039818, 2019). "RNA-sequencing data from 42 meningiomas were obtained from the public database GREIN (GSE101638) and the mean expression level of GREM2 was calculated." (PMID 38446374, 2024). "This study investigated the involvement of Gremlin2 (GREM2), an inhibitor of BMP signaling, particularly the BMP signaling essential for bone formation, in meningioma growth, senescence, and calcification via tryptophan metabolism." (PMID 38446374, 2024). "GREM2 was identified as an upstream regulator of BMP signals in a PubMed keyword search and meningiomas." (PMID 38446374, 2024). "GREM2, SNORA46, and SNORA48 were each expressed at significantly higher levels in grade I meningiomas than grade II and III (p = 0.047, p = 0.017, and p = 0.038, respectively; one-tailed t-test)." (PMID 31039818, 2019). "Among the numerous genes differentially expressed across meningioma grades, we identified GREM2, a regulator of the BMP pathway, and the snoRNAs, SNORA46 and SNORA48, as being significantly reduced in meningioma progression by RNA-seq analysis." (PMID 31039818, 2019). "Among the genes that we have identified as being differentially expressed between grade I and grade II-III tumors are GREM2, SNORA46, and SNORA48, found at higher levels in low grade meningiomas than in higher grade tumors." (PMID 31039818, 2019). "As such, we identify GREM2, a regulator of the BMP pathway, and the snoRNAs SNORA46 and SNORA48, as being significantly reduced in meningioma progression." (PMID 31039818, 2019). "Decrease of GREM2 expression may lead to increase BMP signaling, thus suggesting a role for BMP signaling in meningioma progression." (PMID 31039818, 2019). "GREM2 expression and localization were examined in clinical samples, and GREM2 was found to be almost completely absent in grade 2.3 meningioma by immunostaining, but was strongly expressed around psammoma bodies and at sites of whorl formation grade 1 meningiomas." (PMID 38446374, 2024). "GREM2 function in cancer biology and in meningioma is not known." (PMID 31039818, 2019).